RNU6-790P (RNA, U6 small nuclear 790, pseudogene)
Gene: Small nuclear RNA gene on chromosome 14 (101,803,227 to 101,803,331, forward strand). Ensembl gene ENSG00000207208.
Homologues: Orthologues: macaque U6 (90% identical), rat LOC120093286 (85% identical). Paralogues in human: RNU6-25P (93% identical), RNU6-33P (93% identical), RNU6-1 (92% identical), RNU6-116P (92% identical), RNU6-2 (92% identical), RNU6-35P (92% identical), RNU6-378P (92% identical), RNU6-3P (92% identical), RNU6-48P (92% identical), RNU6-4P (92% identical), RNU6-5P (92% identical), RNU6-6P (92% identical), and 1285 more.